H2AX (H2A.X variant histone)
Diseases named in the same sentence as H2AX in open-access papers (continued):
Sharing a sentence is not in itself a finding about the gene and the disease.
infection (continued). "To further evaluate the effect of these pathways on γ-H2AX expression, we treated RD cells with an ATR inhibitor (VE-821), DNA-PK inhibitor (KU 57788), or ATM inhibitor (KU 55933) at 2 h post infection with EVA71 (MOI = 2)." (PMID 35067196, 2022). "To confirm that SARS-CoV-2 induces cellular senescence per se, we demonstrated that infection of epithelial cells with SARS-CoV-2 virus (B.1.222 strain) in vitro increased SenTraGor staining and induced DNA damage, measured by increased γ-H2AX expression." (PMID 35086840, 2022). "Surprisingly, however, at 24 h post infection with EVA71, the γ-H2AX protein exhibited a cytoplasmic distribution in RD cells." (PMID 35067196, 2022). "Levels of γ-H2AX in RD cells (MOI = 1) and HeLa cells (MOI = 10) were increased after infection with CA16 for 24 h, as well as after infection with CA6 (RD cells, MOI = 5) or EVD68 (RD cells, MOI = 5) for 24 h." (PMID 35067196, 2022). "Upregulation of H2AX in response to an activated DDR has been described previously, and our results argued that d109 infection was sufficient to trigger this response." (PMID 33563816, 2021). "By 8 hpi with both 7134 and 7134R infection, ATM and H2AX phosphorylation were only weakly affected by MRE11A knockout (lanes 9 and 15), arguing that there were redundant pathways for their activation." (PMID 33563816, 2021). "De novo infection of KSHV in human PBMCs or primary endothelial cells upregulates the level of γH2AX, which is the phosphorylated form of H2AX." (PMID 33425783, 2020). "The percentage of cells harboring p-H2AX and FANCD2 foci increased markedly between 4 and 20 h after infection with DH10B pBACpks or treatment with MMC." (PMID 29559578, 2018). "Like WT BMDMs, those that express Cre (Lyz2Cre/+ BMDMs) exhibit robust γ-H2AX formation and KAP-1 phosphorylation in response to infection with L. monocytogenes." (PMID 28362262, 2017). "We conclude that both ATM and DNA-PKcs are activated in BMDMs by LPS and IFN-γ or infection with L. monocytogenes, and that these kinases can have unique (ATM phosphorylation of KAP-1) or overlapping (ATM or DNA-PKcs phosphorylation of H2AX) functions." (PMID 28362262, 2017). "Immunofluorescence staining for phosphorylated H2AX, following Zika MR766 infection displayed characteristic focal pattern of γH2AX known to be induced by DNA damage, unlike mock control or PRVABC59-infected cells." (PMID 29022904, 2017). "During infection by HSV-2, H2AX phosphorylation was similarly dispensable but was dependent on both ATM activity and viral DNA replication." (PMID 26817608, 2016). "Intriguingly, during infection of fibroblasts by HSV-2, H2AX phosphorylation does require viral DNA replication." (PMID 26817608, 2016). "However, the role(s) of H2AX phosphorylation in lytic infection remain unclear." (PMID 26817608, 2016). "Following infection, key components of the DDR, like ATM, RPA, ATRIP, 53BP1, γ-H2AX are recruited into viral replication centers, with PML NBs juxtaposed to these." (PMID 21998700, 2011). "However, γ-H2AX levels are negatively correlated with ATM and DNA-PK activation after EVA71 infection." (PMID 35067196, 2022). "No megalocytosis and no p-H2AX foci were detected in HeLa cells exposed to subsets of ICL-negative strains (n=14 and n=5, respectively), even at a high multiplicity of infection, confirming the deficiency of these strains in colibactin production." (PMID 33961542, 2021). "We did not observe H2AX phosphorylation at 2 hpi following WT infection (lane 7), as we did with d109." (PMID 33563816, 2021). "Phosphorylation of H2AX was readily detected in nuclei of umbrella cells containing IBCs, 6 hours after infection with wild-type E. coli UTI89 with or without the p-clbI-gfp plasmid." (PMID 33630958, 2021).
infection (continued). "MmuPV1 infection induced the expression of phosphorylated H2AX, but not degradation of proapoptotic BAK in the cSCCs." (PMID 33063442, 2020). "In this regard, it has been reported that infection of Huh7.5 cells with HCV resulted in inhibition of histone H4 methylation/acetylation and histone H2AX phosphorylation, with a significant change in expression of genes important for hepatocarcinogenesis, inhibiting DNA damage repair." (PMID 30096846, 2018). "Whereas BMDMs with isolated deficiencies of ATM or DNA-PKcs exhibit a robust DDR, those with deficiencies in both ATM and DNA-PKcs (Scid:AtmC/C:Lyz2Cre/+) exhibit a near-complete abrogation of γ-H2AX and p-KAP-1 formation in response to infection with L. monocytogenes." (PMID 28362262, 2017). "In the present study, infection of porcine circovirus type 2 (PCV2), which serves as a major etiological agent of PCV2-associated diseases (PCVAD), was found to elicit a DNA damage response (DDR) as observed by the phosphorylation of H2AX and RPA32 following infection." (PMID 27982097, 2016). "Following infection of human foreskin fibroblasts by HSV-1 or HSV-2, we assayed the phosphorylation of H2AX in the presence of inhibitors of transcription, translation, or viral DNA replication, or in the presence of inhibitors of ATM and ATR kinases (KU-55933 and VE-821, respectively)." (PMID 26817608, 2016). "CaCo-2 cells infected with MC1-TT exhibited high levels of DNA damage 24h post-infection, assessed by phosphorylation of the histone H2AX (γH2AX), while no specific γH2AX signal was observed in cells infected with the control MC1-ΔcdtB strain." (PMID 27055274, 2016). "Consistent with this, we observed phosphorylation of H2AX in -sni1 plants in the absence of pathogen infection." (PMID 24699527, 2014). "When the rad51d mutant was grown under short-day conditions, it displayed a spontaneous lesion phenotype and exhibited elevated levels of γ-H2AX without pathogen infection." (PMID 24699527, 2014). "We determined whether depletion of H2AX would impact the localization of NBS1 and DNA PKCS, a PI3-like kinase, during infection." (PMID 21589897, 2011). "As predicted, 53BP1 was recruited to ICP0-null viral genomes in wild-type mouse embryonic fibroblasts (MEFs), but did not accumulate during infection of cells lacking H2AX." (PMID 21698222, 2011). "Since far greater than 1% of EBV-infected cells wereγ-H2AX positive early after infection, we conclude that viral lytic DNAreplication is not responsible for DDR activation." (PMID 21147465, 2010). "PRV and VSV infection in HDAC6-KO cells increased acetyl-H2AX by approximately 43% and 13%, respectively, whereas PRV and VSV infection in HDAC6-overexpressing cells decreased acetyl-H2AX by approximately 33% and 22%, respectively, compared to infection in NT cells." (PMID 39861880, 2025). "Interestingly, D-Serine did not reduce γ-H2AX signal intensity upon infection with DH10B pBAC-pks, suggesting that D-Serine activity requires factors specific to the natural colibactin-carrying isolates described here." (PMID 36908282, 2023). "In addition, CV-B5/F infection increased p-DNA-PK, p-ATM, and p-H2AX levels in NCI-H460 cells." (PMID 37743418, 2023). "Moreover, the mRNA levels of H2AX were not affected by EVA71 infection versus mock infection at 24 h post infection in RD cells." (PMID 35067196, 2022). "Furthermore, although ATM is responsible for infection-induced H2AX phosphorylation, neither ATM nor the closely related ATR kinase is strictly required for efficient HSV production." (PMID 26817608, 2016). "Hence it is not overly surprising that Arabidopsis atr atm double mutant plants exhibit heightened disease susceptibility, even though ATM and ATR are not the sole means through which plant H2AX can be phosphorylated after pathogen infection." (PMID 24699527, 2014).
infection (continued). "To determine whether infection with L. monocytogenes activates this pathway, we focused on three well-characterized DDR markers: accumulation of poly-ADP ribosylated proteins, phosphorylation of H2AX and increase in the number of 53BP1 foci." (PMID 25340842, 2014). "Infection of HeLa cells with mutant M1/5 entD clbA did not induce phosphorylation of H2AX." (PMID 23853582, 2013). "In addition, immuno-staining for the phosphorylated form of the histone H2AX, an early marker of double strand breaks, displayed a nearly complete staining of the nuclei following infection of Ad-Control, but absent in Ad-199T-infected livers." (PMID 24069256, 2013). "Thus, induction of H2AX phosphorylation is not triggered merely by the presence of viral DNA in the infected cell nor by replication of viral DNA, but by expression of some viral or cellular protein following infection." (PMID 26817608, 2016). "Next, we investigated viral genome replication; the amount of viral genome was equivalent in wild-type and knockout cells at 4 h after infection with EVA71 (MOI = 10), indicating that γ-H2AX did not inhibit viral entry." (PMID 35067196, 2022). "In the same way as was seen with p-H2AX/FANCD2 foci, 53BP1 and RPA colocalized in subnuclear foci in a time-dependent manner in MMC-treated or pks+E. coli-infected cells but not after infection with E. coli hosting the pBAC vector." (PMID 29559578, 2018). "Interestingly, the γ-H2AX band induced by Pst migrated slightly slower in SDS-PAGE than that induced by gamma-rays, suggesting that additional sites may be phosphorylated upon pathogen infection other than the highly conserved serine at the C-terminus of H2AX protein." (PMID 24699527, 2014). "We found that the expression of p-H2AX, cleaved-caspase 3, and lipidated LC3B (LC3B II) was upregulated in siDNA-PK-treated and siATM-treated groups compared to the negative control group after CV-B5/F infection." (PMID 37743418, 2023). "We next asked whether the DNA damage response was activated specificallyduring the hyper-proliferative divisions independent of time post infection.EBV-infected B cells sorted based on population doubling (PD) were subjected toimmunofluorescence for EBNA-LP and γ-H2AX." (PMID 21147465, 2010).
adenocarcinoma (4 papers, 2010 to 2023). A common cancer characterized by the presence of malignant glandular cells. "Notably, inhibition of USP28 in human adenocarcinoma cell lines, and in the SCC line SiHa, which does not express ∆Np63, led to a reduction of ɣ-H2AX, and co-treatment with cisplatin had no additive nor synergistic effect." (PMID 34611298, 2022).
neurodegenerative disease (4 papers, 2014 to 2024). A disorder of the central nervous system characterized by gradual and progressive loss of neural tissue and neurologic function. "In traumatic brain injury or neurodegenerative diseases, H2AX has been shown to be a sensitive marker of DNA damage through phosphorylation of its serine residue at Ser139 (γH2Ax)." (PMID 38464175, 2024). "Our findings that deficiency of the DNA repair histone H2AX leads to accumulation of mitochondrial-derived ROS and neurobehavioral deficits imply a key role for H2AX in aging and neurodegenerative diseases." (PMID 29670103, 2018). "Therefore, targeting H2AX and/or DDR-related molecules looks to be a promising strategy to develop new approaches to counteract neurodegeneration, as the loss of function of DDR proteins (among which γH2AX) appears to be tightly linked to several neurodegenerative diseases." (PMID 24451138, 2014).
bacterial infection (2 papers, 2020 to 2025). "Both deletion and overexpression of clbQ in E. coli M1/5 resulted in reduced levels of γ-H2AX upon bacterial infection of HeLa cells as well as in significant reduction of C14-Asn levels." (PMID 32669458, 2020).
genetic disease (2 papers, 2012 to 2023). "For each genetic disease, some proteins specifically overexpressed in the cytoplasm and interacting with the ATM protein may sequester the ATM monomers in the cytoplasm and prevent their diffusion in the nucleus and the phosphorylation of H2AX histones at the DSB sites." (PMID 37626928, 2023).
kidney diseases (2 papers, 2020 to 2025). "Therefore, DNA damage detected by γ-H2AX in the glomerulus is a good prognostic marker for kidney diseases, particularly those with nodular glomerulosclerosis." (PMID 33335142, 2020).
inflammation (1 paper, 2015). Aberrant reaction of the microcirculation characterized by movement of fluid and leukocytes from the blood into extravascular tissues. "To learn if pancreatic inflammation induces DSBs in vivo, we analyzed the frequency of DSB repair foci by quantifying cells with five or more γH2AX foci (H2AX becomes phosphorylated to form γH2AX in the vicinity of DSBs)." (PMID 25647331, 2015).
retinopathies (1 paper, 2012). "Recent evidence suggests that such activation of H2AX contributes to angiogenesis and proliferative retinopathies." (PMID 22545090, 2012).
H2AX also shares sentences with these, for which no sentence is quoted: medulloblastoma (5 papers); head and neck squamous cell carcinoma (4); acute lymphoblastic leukemia (3); non-Hodgkin lymphoma (3); breast adenocarcinoma (2); dementia (2); esophageal squamous cell carcinoma (2); heart disease (2); multiple myeloma (2); prion disease (2); systemic lupus erythematosus (2); ulcerative colitis (2); acromegaly (1); Allergy (1); anal carcinoma (1); aneurysm (1); Anxiety (1); atherosclerosis (1); atopic eczema (1); B-cell neoplasm (1); basal cell carcinoma (1); bile duct cancer (1); cardiomyopathy (1); cardiovascular diseases (1); cerebellar tumor (1); Cerebral ischemia (1); cervical adenocarcinoma (1); chronic hepatitis B (1); chronic hepatitis C virus infection (1); ciliopathy (1).
A further 66 diseases each share a sentence with H2AX in 1 paper.